QRSL1 (glutaminyl-tRNA amidotransferase subunit QRSL1)
Description:
Allows the formation of correctly charged Gln-tRNA(Gln) through the transamidation of misacylated Glu-tRNA(Gln) in the mitochondria. The reaction takes place in the presence of glutamine and ATP through an activated gamma-phospho-Glu-tRNA(Gln).
Synonyms: GatA; FLJ10989; FLJ12189; DKFZP564C1278; FLJ13447; COXPD40
Tractability: PROTAC: ubiquitination databases record sites on it; its protein half-life has been measured.
Gene: Protein-coding gene on chromosome 6 (106,629,572 to 106,668,417, forward strand). Ensembl gene ENSG00000130348.
Subcellular location: Mitochondrion
Subcellular location (Human Protein Atlas): Vesicles; Centrosome
Gene Ontology:
Molecular function: glutaminyl-tRNA synthase (glutamine-hydrolyzing) activity; protein binding; carbon-nitrogen ligase activity, with glutamine as amido-N-donor; catalytic activity; glutaminase activity
Biological process: glutaminyl-tRNAGln biosynthesis via transamidation; mitochondrial translation; translation
Cellular component: glutamyl-tRNA(Gln) amidotransferase complex; mitochondrion
Genetic constraint (gnomAD): Loss-of-function variants: 49 observed, 56.24 expected, observed/expected ratio (o/e) 0.87, 90% interval 0.69 to 1.11. The upper end of that interval is the gene's LOEUF score, 1.11, which puts it in group 4 of 6, group 1 being the genes least tolerant of losing a copy. Missense variants: 493 observed, 629.54 expected, observed/expected ratio (o/e) 0.78, 90% interval 0.73 to 0.84. Synonymous variants: 221 observed, 227.89 expected, observed/expected ratio (o/e) 0.97, 90% interval 0.87 to 1.08.
Homologues: Orthologues: chimpanzee QRSL1 (100% identical), macaque QRSL1 (93% identical), pig QRSL1 (93% identical), dog QRSL1 (92% identical), rabbit QRSL1 (91% identical), mouse Qrsl1 (88% identical), rat Qrsl1 (87% identical), guinea pig QRSL1 (86% identical), tropical clawed frog qrsl1 (74% identical), zebrafish qrsl1 (65% identical), Drosophila melanogaster GatA (51% identical), Caenorhabditis elegans Y41D4A.6 (39% identical). Paralogues in human: FAAH2 (23% identical), FAAH (18% identical).
Diseases named in the same sentence as QRSL1 in open-access papers:
QRSL1 is named in the same sentence as 77 diseases in open-access papers, as found by Europe PMC text mining. Sharing a sentence is not in itself a finding about the gene and the disease. The quoted sentences say what the papers report.
breast carcinoma (11 papers, 2017 to 2025). "In addition, ROC analysis revealed that the four genes had higher AUC values for predicting the diagnosis of breast cancer (TBC1D24, AUC = 0.798; TRIM67, AUC = 0.711; ZDHHC9, AUC = 0.810; QRSL1, AUC = 0.801)." (PMID 37875591, 2023).
ovarian carcinoma (5 papers, 2009 to 2025). A malignant neoplasm originating from the surface ovarian epithelium. "The differential expression of CCDC170, MTRF1L, ZBTB2, ARMT1, PLEKHG1 and QRSL1 genes affected the overall survival (OS) of ovarian cancer patients." (PMID 37024829, 2023).
Adrenal insufficiency (1 paper, 2016). Insufficient production of steroid hormones (primarily cortisol) by the adrenal glands. "Pt250, a girl with tachypnea, hypertrophic cardiomyopathy, adrenal insufficiency, hearing loss, and combined respiratory chain complex deficiencies (I, II, III, and IV), harbored a homozygous mutation c.398G>T (p.G133V) in QRSL1 (NM_018292)." (PMID 26741492, 2016).
deficiencies (1 paper, 2016). "We newly confirmed 3 mitochondria-related genes (MRPS23, QRSL1, and PNPLA4) as causative genes of mitochondrial respiratory chain complex deficiencies." (PMID 26741492, 2016). "We ultimately identified 41 mutations, of which 37 were novel, in 20 genes that were previously reported to cause OXPHOS disease and 3 novel mitochondria-related genes (MRPS23, QRSL1, and PNPLA4) as causative genes of mitochondrial respiratory chain complex deficiencies." (PMID 26741492, 2016).
multiple sclerosis (1 paper, 2024). A progressive autoimmune disorder affecting the central nervous system resulting in demyelination. "Thirdly, genetic susceptibility to multiple sclerosis (MS) was linked to higher IL-6 responses through the QRSL1 locus." (PMID 38714679, 2024).
cancer (26 papers, 2003 to 2025). A tumor composed of atypical neoplastic, often pleomorphic cells that invade other tissues. "To predict the cancer-promoting characteristics and prognosis of TNBC using the combination of the four genes, we calculated risk coefficients for co-expression integration and constructed a risk model with the following formula: risk score = 2*TBC1D24 + 1*TRIM67 + 1*QRSL1 + 1.8*ZDHHC9." (PMID 37875591, 2023).
mitochondrial disease (1 paper, 2016). "We identified 3 novel disease-causing mitochondria-related genes (MRPS23, QRSL1, and PNPLA4) as well as other disease-causing genes and novel pathogenic mutations in known mitochondrial disease-causing genes." (PMID 26741492, 2016). "We identified 37 novel mutations in known mitochondrial disease genes and 3 mitochondria-related genes (MRPS23, QRSL1, and PNPLA4) as novel causative genes." (PMID 26741492, 2016).
QRSL1 also shares sentences with these, for which no sentence is quoted: tumor (30 papers); infection (13); lung carcinoma (5); anemia (4); cardiac hypertrophy (4); bladder cancer (3); leukemia (3); neuroblastoma (3); osteoporosis (3); prostate carcinoma (3); Astigmatism (2); bacterial infection (2); cardiac diseases (2); congenital heart disease (2); gastric cancer (2); hypoparathyroidism (2); idiopathic pulmonary fibrosis (2); lung adenocarcinoma (2); pancreatic cancer (2); acute leukemia (1); acute megakaryoblastic leukemia (1); acute myeloid leukemia (1); asthma (1); atrial septal defect (1); atrioventricular septal defect (1); Barrett's oesophagus (1); cardiovascular diseases (1); central nervous system diseases (1); cervical cancer (1); cholangiocarcinoma (1).
A further 40 diseases each share a sentence with QRSL1 in 1 paper.